FOS (Fos proto-oncogene, AP-1 transcription factor subunit)
Diseases named in the same sentence as FOS in open-access papers (continued):
Sharing a sentence is not in itself a finding about the gene and the disease.
fibroma of (1 paper, 2023). "To explore the specificity of these findings in FOS and FOSL1 for desmoplastic fibroblastoma, we examined 15 fibroma of tendon sheath tumours, their principal histological mimic." (PMID 36426824, 2023).
follicular thyroid carcinoma (1 paper, 2025). "Our current study’s findings are consistent with our previous research, further substantiating that the FOS and JUN genes serve as potential molecular markers for diagnosing thyroid malignancies, particularly follicular thyroid carcinoma (FTC)." (PMID 40722651, 2025).
HIV-1 infection (1 paper, 2024). The type species of lentivirus and the etiologic agent of acquired immunodeficiency syndrome (AIDS). "In the gene-pathway connections, multiple molecules and kinases for NF-κB signaling (e.g., IKBKB, JUN, FOS, MAP2K2, NFKBIA, TLR4) connected the HIV-1 infection and other inflammatory or anti-viral pathways." (PMID 39283947, 2024).
Hyperammonemia (1 paper, 2023). An increased concentration of ammonia in the blood. "FOS-cre ERT2 (TRAP2) mice, together with applications of tamoxifen and viral vectors containing double floxed sites (DIO), are used to screen the brain area sensitive or susceptible to HE-induced hyperammonemia." (PMID 37488119, 2023). "The current research indicates the hyperammonemia level could directly activate GABAergic neurons within the SNr, reflecting as the expression of activation marker FOS." (PMID 37488119, 2023).
Hyperesthesia (1 paper, 2024). Increased sensitivity to stimulation, excluding the special senses, which may refer to various modes of cutaneous sensibility including touch and thermal sensation without pain, as well as to pain. "Then, component of this activated MAPK (c-MAPK) translocates to the nucleus resulting in elevated expression of transcription factors c-Myc, Elk-1, c-FOS and c-Jun, and caused hyperesthesia eventually." (PMID 38368171, 2024).
hypopharyngeal carcinoma (1 paper, 2025). Carcinoma, predominantly squamous cell, arising from the epithelial cells of the hypopharynx. "Moreover, we observed significant upregulation of the MAPK pathway-associated gene FOS in hypopharyngeal cancer tissues." (PMID 40649749, 2025). "In light of these findings, it is plausible to suggest that sncRNAs may contribute to the development and progression of hypopharyngeal carcinoma by modulating the expression of FOS, thereby mediating the MAPK signaling pathway." (PMID 40649749, 2025). "The results showed that the expression levels of FOS (an MAPK pathway-related gene), SERPINE1 (a TGF-β pathway-related gene), and BCL2L11 (a FoxO pathway-related gene) were significantly higher in hypopharyngeal carcinoma tissues than in adjacent non-tumor tissues." (PMID 40649749, 2025).
intestinal tumor (1 paper, 2016). "In conventional C57BL/6J Min/+ mice, inulin has been reported to increase the genetically driven small intestinal tumor burden except for one study reporting short chain FOS (which can be produced by degradation of inulin) to attenuate tumorigenesis." (PMID 27196124, 2016).
keratoconus (1 paper, 2020). A degenerative, structural disorder of the eye, characterized by a cone-shaped protrusion of the cornea. "The gene encoding cyclic AMP dependent transcription factor ATF3, decreased in both groups, regulates cell proliferation and differentiation, and is a stress response gene that interacts with JUN and FOS; additionally, related genes, JUND and FOLSL1 are both downregulated in the keratoconus samples." (PMID 32555404, 2020).
latent infection (1 paper, 2024). "Based on these results, we hypothesized that, in the absence of ORF57 or during KSHV latent infection, FOS RNA is destabilized by a host destabilizer (s) and has a short half-life." (PMID 38410462, 2024).
leiomyoma (1 paper, 2020). A well-circumscribed benign smooth muscle neoplasm characterized by the presence of spindle cells with cigar-shaped nuclei, interlacing fascicles, and a whorled pattern. "This study establishes the loss of FOS and JUN gene expression in leiomyoma tissues, along with the resulting depletion of AP-1 chromatin occupancy, as likely significant events in leiomyoma disease pathogenesis." (PMID 32094355, 2020). "Two thousand nine hundred and ninety-three out of 25,736 FOS peaks were differentially bound in leiomyoma tissue samples with 86% of altered binding sites (n = 2573/2993) showing a loss in binding affinity." (PMID 32094355, 2020). "Notably, expression of the JUN, FOS, and ATF families of genes was down-regulated in leiomyoma tissue." (PMID 32094355, 2020).
lentivirus infection (1 paper, 2021). Virus diseases caused by the Lentivirus genus. "Therefore, we overexpressed FOS and JUN in HASMCs via lentivirus infection." (PMID 34485398, 2021).
leukopenia (1 paper, 2024). "Furthermore, JUN and FOS were identified as key regulators in multiple pathways related to leukopenia treatment." (PMID 39295929, 2024). "Interestingly, multiple pathways involved in JUN and FOS may be key genes for QJSB in the treatment of leukopenia." (PMID 39295929, 2024). "Transcriptomics results showed changes in the expression of JUN, FOS, and HGF genes in both the model group and the QJSB group, further supporting the potential role of QJSB in regulating cell growth processes for the treatment of leukopenia." (PMID 39295929, 2024).
lipidosis (1 paper, 2017). "Moreover, adipocytokines IL6 and Leptin, in addition the genes, EGR1, FOS, SERPINE1, AGT and MMP2 might have great impacts on adipocyte differentiation and lipidosis." (PMID 28706200, 2017).
lung diseases (1 paper, 2020). "Among the over-represented TFs in PETGenes, NF-KB1, CREB, STAT, FOS, and JUN, have been reported to play a critical role in regulating inflammation in lung diseases, and we extracted their TFBS in the promoter region of their target genes." (PMID 33643286, 2020).
mastitis (1 paper, 2024). Inflammation of breast tissue during lactation or postpartum due to an obstructed duct or infection. "This may also indicate that the FOS gene regulates SCC, or mastitis resistance, by influencing arginine metabolism." (PMID 39596441, 2024).
meningeal tumors (1 paper, 2017). "Additionally, FOS, MYC, and PDPN have been shown to be overexpressed specifically in meningeal tumors." (PMID 29073243, 2017).
meningioma (1 paper, 2012). A generally slow growing tumor attached to the dura mater. "Considering inconsistent expression of SOS2/KRAS and JUN/FOS in fibroblastic meningioma, we speculated that activated Ras promoted tumor growth through the PI3K/Akt pathway, but not via ERK-c-Jun/c-Fos pathway." (PMID 23285163, 2012).
metastatic melanoma (1 paper, 2013). A melanoma that has spread from its primary site to another anatomic site. "Considering that metastatic melanomas are frequently characterized by BRAF V600E heterozygous mutation, we assessed its role on c-FOS stability by transiently transfecting BRAF V600E in the early primary Me1007 cell line, endogenously expressing wild-type BRAF." (PMID 23400877, 2013).
Miscarriage (1 paper, 2025). A pregnancy that ends at a stage in which the fetus is incapable of surviving on its own, defined as the spontaneous loss of a fetus before the 22th week of pregnancy. "Three significant genes – FOS, FOSB, and LY96 – associated with miscarriage were identified; these genes are up-regulated during infection but suppressed by the vaccine." (PMID 41232126, 2025). "Further research on 17 core enriched genes expressed at the MFI indicated that CXCL11, MMP10, FOS, FOSB, LY96, and NCF2 may be closely related to miscarriage." (PMID 41232126, 2025).
myocarditis (1 paper, 2022). Myocarditis is a condition that is characterized by inflammation of the heart muscle (myocardium). "In addition, genes involved in the regulatory network of JUN and FOS were mostly downregulated during myocarditis in classical monocytes." (PMID 36225942, 2022). "Thus, in contrast to JUN and FOS down-regulated at the time of myocarditis, metabolism-related genes were significantly up-regulated." (PMID 36225942, 2022). "Considering that monocytes in acute myocarditis show altered JUN/FOS activity, along with changes in the metabolism-related gene pathway, further investigation is required to determine whether monocytes in acute myocarditis resemble monocyte-derived macrophages activated without prior priming." (PMID 36225942, 2022).
myosarcoma (1 paper, 2019). "As the interaction network of upregulated and downregulated miRNAs displays, we found that FOS, TGFB1, RB1 and ID2 are important genes controlling proliferation and apoptosis in myosarcoma." (PMID 30717351, 2019).
nephritis (1 paper, 2015). Inflammation of renal tissue. "This more liberal view revealed FOS and LINC00339 (induction linked to nephritis), as well as MZB1 and TXNDC5 (induced in Type B patient samples), as increased in patients under steroid treatment." (PMID 26544975, 2015). "Mann-Whitney analysis detected 139 genes at the p<0.05 threshold, of which only FOS, LINC00339, and C1orf86 had been previously noted (all increased in nephritis)." (PMID 26544975, 2015).
periodontal disease (1 paper, 2024). "An overexpression of CTNNB1, FOS, JUN, GRB2, PIK3CA, and PIK3R1 may affect the cell cycle, resulting in excessive cell proliferation, and malignant transformation, besides being related to periodontal disease development and progression." (PMID 39517401, 2024).
pilocytic astrocytoma (1 paper, 2016). Pilocytic astrocytoma is a rare subtype of low-grade glioma of the central nervous system characterized by a well circumscribed, often cystic, brain tumor with a discrete mural nodule and long, hair-like projections that extend from the neoplastic astrocytes. "The AP-1 transcription factor complex, activated by the MAPK pathway, is predicted to bind at a number of these CpG sites, and FOS transcription factors are up-regulated in pilocytic astrocytomas." (PMID 27229157, 2016).
pituitary adenoma (1 paper, 2014). "The PPI network of the downregulated DEGs in pituitary adenoma exhibited centralization, and certain node proteins of the network, including EGR1, STAT3, JUNB and FOS, were the common transcription factors in cancer; the PPI network of upregulated DEGs was sparsely populated." (PMID 25360166, 2014).
primary immunodeficiency (1 paper, 2025). "FOS was associated with complement and coagulation cascades, Fc-gamma receptor (FcγR)-mediated phagocytosis, primary immunodeficiency, ribosome, spliceosome, and Toll-like receptor signaling pathway." (PMID 40574839, 2025).
pulpitis (1 paper, 2021). Inflammation of the dental pulp. "Several transcription factors have been identified to be involved in the TF-gene regulatory network of pulpitis, including GATA2, ETS1, FOXP3, STAT1, FOS, and JUN." (PMID 33777260, 2021). "Six transcription factors (i.e., GATA2, ETS1, FOXP3, STAT1, FOS, and JUN) were identified to play pivotal roles in pulpitis." (PMID 33777260, 2021).
Retinal hemorrhage (1 paper, 2021). Bleeding located within the retina. "Therefore, FOS may be associated with the leakage of the peripheral retinal vessels and retinal hemorrhages in HAR through the regulation of inflammatory constituents." (PMID 33393628, 2021).
rosacea (1 paper, 2021). A chronic erythematous skin disorder that affects the face. "Our results were consistent with the hypothesis that AP1 TFs (FOS, FOSB, JUN and JUND) were downregulated in rosacea lesions." (PMID 34290700, 2021).
seminoma (1 paper, 2013). A radiosensitive malignant germ cell tumor found in the testis (especially undescended), and extragonadal sites (anterior mediastinum and pineal gland). "One study found that ERK1/2 – an intermediate of the GDNF pathway that leads to activation of FOS and other target genes, was increasingly phosphorylated in more than half of 26 seminomas potentially altering expression of downstream targets of the RAS/ERK1/2 pathway including FOS and ATF." (PMID 23519268, 2013).
sensorineural hearing loss (1 paper, 2018). "Among the top most significant associations that were found only by functional annotation filtering of variants, we identified associations between the FOS gene with “sensorineural hearing loss” ICD-9 389.10." (PMID 29545597, 2018).
Sleep apnea (1 paper, 2023). An intermittent cessation of airflow at the mouth and nose during sleep is known as sleep apnea. "The results showed that Lasso regression identified a total of seven genes as the characteristic genes of sleep apnea, which are: C12orf54, FOS, GPR1, OR9A4, MYO5B, RAB39B, KLHL4, as the core genes of follow-up research and construction of prediction models." (PMID 38077447, 2023).
subarachnoid hemorrhage (1 paper, 2013). A serious neurological disorder characterized by intracranial hemorrhage into the subarachnoid space. "This study aimed to observe the expression of FOS protein in the rat MVZ following subarachnoid hemorrhage (SAH) and the severing of the celiac branches of the vagus nerve, as well as provide experimental evidence to clarify the neuroendocrine and immunological mechanisms of MODS caused by ACVD." (PMID 23251272, 2013). "This study was designed to observe the role of FOS protein expression in the rat medullary visceral zone (MVZ) in multiple organ dysfunction syndrome (MODS) caused by subarachnoid hemorrhage (SAH), with and without severing the vagus nerve." (PMID 23251272, 2013).
synovitis (1 paper, 2018). Inflammation of a synovial membrane. "Genes such as NRAS, SPHK2, FOS, CXCR4, PLD1, GNAI2, and PLA2G4F were strongly implicated in synovitis of OA." (PMID 29968759, 2018).
T-cell lymphoma (1 paper, 2012). "A previous study had determined the mRNA expression profile of EBV-infected nasal NK/T-cell lymphoma lines and found, among others, the IL1A, BCL6, CD44 and c-FOS genes to be induced and the interleukin 1 receptor 1 (IL1R1) gene to be repressed compared to normal lymphocytes." (PMID 22870299, 2012).
tauopathies (1 paper, 2022). "Immunohistochemical analysis in postmortem brain tissue of individuals with the very rare 3R tauopathy Pick's disease revealed colocalization of AP-1 components such as FOS, JUN, and MYC with the disease-defining intraneuronal pTau deposits (Pick bodies) and neuronal cytoplasms." (PMID 35976433, 2022). "In a subsequent step, overall feature importance assessment highlighted IER- and cellular immunity-related TFs (FOS, JUN, NFATC2/3, STAT1) as most useful in predicting the tauopathy or Ctrl state." (PMID 35976433, 2022). "Thus, to discriminate the two tauopathies, we hereby propose JUN(B,D)HIGH, FOS(L1,L2)HIGH as well as the involvement of DUX4, KLF5, MAX::MYC, PAX6, and PPARG to support the identity of CBD-originated astrocytes." (PMID 35976433, 2022).
thyroid (1 paper, 2025). "In the comparison between PTC and benign thyroid samples, SFN and CCNA1 were significantly upregulated, whereas FOS, HSPA5, JUN, CREB1, and MAP2K6 exhibited significant downregulation, supporting the findings obtained from the RT-qPCR analysis." (PMID 40722651, 2025).
Umbilical hernia (1 paper, 2020). Protrusion of abdominal contents through a defect in the abdominal wall musculature around the umbilicus. "Another gene found in a QTL region for umbilical hernia is the FOS, which was upregulated in affected pigs and validated by qPCR." (PMID 32379844, 2020).
uveal melanoma (1 paper, 2025). A melanoma derived from melanocytes of the uveal tract. "The STRING analysis performed in plasma samples of uveal melanoma patients for miR-155-5p showed that the molecules with the most interaction of the miR-155-5p were CBL and RAP1B proteins along with FOS and ETS1 (p value: 0.000399)." (PMID 38914847, 2025).
Venous thrombosis (1 paper, 2025). Formation of a blood clot (thrombus) inside a vein, causing the obstruction of blood flow. "In summary, our study has revealed several crucial genes, including FOS, ICAM1, CASP3, and HSP90AA1, which likely play pivotal roles in the therapeutic effects of herbal medicine against venous thrombosis." (PMID 41327671, 2025).
tumor (441 papers, 1998 to 2026). "In the interaction network between fib2 and malignant cells, we identified a key axis involving LGALS3BP–ITGB1–JUN/FOS–TGFβ1, which is primarily associated with tumor migration, cell adhesion, and angiogenesis." (PMID 40725477, 2025). "Among them, c‐FOS, a core component of the activator protein‐1 (AP‐1) complex, has been closely associated with tumor progression, chemoresistance, and apoptosis, which supported its selection for in‐depth investigation." (PMID 40598817, 2025). "This underlined the important tumor-promoting action of FOS, which was essential in the evolution of TCs." (PMID 40936936, 2025). "Pathway analysis of FOS overexpression hotspots in high-violence tumor samples found pathways associated with angiogenesis, the cell membrane, and sphingolipid metabolism." (PMID 38912926, 2024). "c-JUN and c-FOS, both well-established oncogenes, are considered to play a critical role in tumorigenesis, proliferation and transformation, angiogenesis, tumour invasion and metastasis, and their expression is associated with poor clinical outcomes." (PMID 36830725, 2023). "The FOS gene encodes the C‐FOS protein, and its expression was negatively associated with tumour progression in patients with GC." (PMID 37118990, 2023). "Both, proapoptotic BCL-2 or MAP kinase pathway members (BIK, BAK1, MAP3K12, and MAPK9) and proliferation-associated tumor drivers (FOS, HOXA3, and POLR2B) had an increased gene expression." (PMID 35778418, 2022). "BCL2, c-FOS and HIF1a are transcription factors, whose dysregulation were broadly reported to be associated with tumor inflammation, angiogenesis, and suppression of apoptosis among others." (PMID 31754348, 2019). "These include EGR1, which is known to bind to the ZFP36 promotor and regulate a number of factors associated with tumor progression in mammary gland tumors, including FOS." (PMID 29073243, 2017). "As an AP-1 component, FOS has been implicated in the regulation of various cellular processes such as enhanced proliferation, apoptosis, and tumor metastasis." (PMID 26571389, 2015). "Many studies reported that FOS modulated several important genes for tumourigenesis, causing the down-regulation of tumour-suppressor genes and leading to invasive growth of cancer cells." (PMID 24865347, 2014). "Consistently, RasV12/lgl−/− tumour in larva obviously increased the mRNA level of c-FOS that encodes one component of AP-1 (JNK downstream transcription complex), and the increased c-FOS transcription was notably impeded by XFZYD at the concentration of 3.13 g/L through a qRT-PCR assay." (PMID 35903326, 2022). "Alterations in FOS expression have been associated with malignant phenotypic changes in tumor cells, while downregulation of CCL2 and CAV1 may influence immune cell recruitment and signaling within the tumor microenvironment, thereby affecting tumor immune evasion and progression." (PMID 41155558, 2025). "FOS might play vital roles in neoplasia and progression in BC as a TF and immune‐associated gene." (PMID 35037412, 2022). "Some studies showed that overexpression of FOS might be associated with inhibition of tumor." (PMID 30228980, 2018). "Furthermore, the deregulation of FOS might associate with tumor progression and oncogenic transformations." (PMID 30301189, 2018). "The co-expressed gene FOS was upregulated in the “invasive cancer + stroma + lymphocytes” spatial region, potentially suppressing tumor development and enhancing response to paclitaxel treatment." (PMID 41123022, 2026). "ex., typical tumor drivers BCAN, APOE, and EGFR or genes associated to neuronal function like EGR1, FOS, and MARCKS)." (PMID 40188875, 2026).